CXCR2 (C-X-C motif chemokine receptor 2)
Diseases named in the same sentence as CXCR2 in open-access papers (continued):
Sharing a sentence is not in itself a finding about the gene and the disease.
tumor (continued). "Inhibition of CXCR2 abolishes all tumor processes involving the CXCL1-CXCR2 axis." (PMID 40427171, 2025). "Moreover, CXCR2 inhibition has been shown to increase NK cell infiltration in tumours, which is consistent with other findings in the field." (PMID 41163221, 2025). "Activation of CXCR2 by CXCL3 promoted a phenotypic transition from fibroblasts to myofibroblast-like cancer-associated fibroblasts, marked by α-smooth muscle actin expression, ultimately promoting tumor metastasis." (PMID 41259383, 2025). "Furthermore, the spatial analysis revealed that CXCR2+ neutrophils are located distally from high-EHF tumor cells but proximally to low-EHF tumor cells." (PMID 41007733, 2025). "Consequently, CXCR2 inhibitors have the potential to reprogram the NASH-HCC tumor immune microenvironment, fostering a more favorable response to immune checkpoint inhibitors." (PMID 40260303, 2025). "By disrupting neutrophil recruitment, therapies targeting CXCR2/CXCL8 may enhance the immune response against the tumor and improve the efficacy of other cancer treatments, including immunotherapies." (PMID 40486614, 2025). "Furthermore, CXCR2 and XCR1 are associated with the metastatic potential at the forefront of tumor invasion." (PMID 41445742, 2025). "Furthermore, in a coculture system of RM-1/CXCR2 tumour cells with spleen-derived macrophages, CD36 inhibition markedly reduced M2 polarization." (PMID 41163221, 2025). "The CXCR2 antagonist SB225002 has shown anti‐tumor activity in several cancers." (PMID 40145793, 2025). "Immune-related genes, such as chemokine (Cxcr2), C-type lectin (Clec4e), chemokine ligand (Cxcl3), tumor growth-related genes, galectin-7 (Lgals7), and matrix metallopeptidase 8 (Mmp8), were downregulated by colonization of B. plebeius in colon tissues of the mice exposed to AOM/DSS." (PMID 39804065, 2025). "In the tumor microenvironment, PKM2 promotes tumor cells to release cytokines and aggregates a large number of MDSCs around tumor cells, PKM2 facilitates the binding of cytokines, such as CXCL1 and MIF, released by tumor cells to the surface receptors CXCR2 or CXCR4 on MDSCs." (PMID 40948745, 2025). "Interestingly, CRC can produce CXCL8 themselves and increase the levels of CXCR1 and CXCR2, which helps the tumor grow, spread, and form metastases." (PMID 40943634, 2025). "For example, CXCR1 and CXCR2 are known to facilitate the recruitment of neutrophils to tumor sites, promoting tumor cell proliferation and angiogenesis, both of which are crucial for tumor growth and metastasis." (PMID 41024311, 2025). "In the present study, we used double-knockout mice for CCR1 and CXCR2 in BM transfer experiments, and discovered that simultaneous deletion of both CCR1 and CXCR2 entirely inhibited neutrophil mobilization, thereby significantly suppressing tumor growth and metastasis." (PMID 38750114, 2024). "Therefore, the overexpression of chemokine receptors such as CXCR2 has been used to improve CAR T cell migration to tumor tissues." (PMID 38554158, 2024). "They engineered CARs modified with IL-8 receptors, CXCR1, and CXCR2, demonstrating that these modified CARs could be guided to migrate into tumors, inducing an enhanced anti-tumor response in solid tumors." (PMID 39134804, 2024). "Previous study showed that CAFs could mediate resistance to CSF-1R therapy by secreting CXCL1 and CXCL2 to recruit PMN-MDSCs, and the combined inhibition of CXCR2 and CSF-1R could overcome tumor resistance." (PMID 38291516, 2024). "CXCL1 is chemotactic of CXCR2 expressing CAR T-cells toward the tumor." (PMID 38612592, 2024). "Our findings also show that CXCR2 inhibition reduces neutrophil migration toward tumor spheroids." (PMID 38898176, 2024). "Collectively, our analysis suggests that Cxcr2 is important to neutrophil function in the tumor-bearing setting within CRCLM, and this stimulus may be derived from tumor cell and microenvironmentally produced chemokines." (PMID 38358352, 2024).
tumor (continued). "CXCR1 and CXCR2 are highly expressed by CD56dim NK cells and facilitate their tumor infiltration." (PMID 39339180, 2024). "Similarly, modification of the chemokine receptors CXCR1/CXCR2/CXCR5 to the surface of CAR-T cells can increase cellular transport within the tumor and anti-tumor efficacy." (PMID 38911868, 2024). "This suggests that CXCR2 is not required to induce the maximum immunosuppressive effect seen in tumor-associated neutrophils within the CRCLM microenvironment and does not alter neutrophil phenotype in health." (PMID 38358352, 2024). "Hence, CXCR2 inhibition via AZD-5069 attenuated dHL-60 cell-induced invasion of PANC-1 tumor spheroids only when they were allowed to engage in direct contact with dHL-60 cells." (PMID 38898176, 2024). "Dual treatment with CCR2 and CXCR2 inhibitors can significantly increase the suppression of tumor-infiltrating myeloid cells in PDAC compared with either strategy alone and enhance the chemotherapeutic efficacy of FOLFIRINOX (5-Fluorouracil, irinotecan, and oxaliplatin)." (PMID 38672552, 2024). "Therefore, we investigated the role of CXCR2 in myeloid cells using two syngeneic CRC mouse models of MC38 cells: a transplanted tumor model and a liver metastasis model." (PMID 38750114, 2024). "Next, we investigated the effect of CXCR2 deletion of the host mice in MC38 tumor models." (PMID 38750114, 2024). "CXCR2 genes were more highly expressed in normal samples compared to tumour samples." (PMID 38426619, 2024). "Activated STAT3, NF-κB, JAK/STAT pathway, and CXCR-2 in tumor." (PMID 39906741, 2024). "An important question is whether CXCR2 inhibition attenuates neutrophil-promoted tumor progression via blocking release of soluble factors by neutrophils or blocking direct contact between neutrophils and cancer cells." (PMID 38898176, 2024). "Interestingly, the upregulation of CXCR2 is predominantly confined to neutrophils, with minimal expression observed in tumor cells." (PMID 39638788, 2024). "The IL-8/CXCR2 axis may have an important role in tumour progression and invasion by maintaining and promoting the migration of CSCs." (PMID 39199570, 2024). "Also, the combination of CCR2 and CXCR2 inhibitors can interrupt the accumulation of CCR2+ TAMs and CXCR2+ tumor-associated neutrophils (TANs) in the TME and enhance the effectiveness of chemotherapy in treating PDAC." (PMID 38835055, 2024). "Therefore, the limitations of currently available traditional tools render a full depiction of the tumor-promoting mechanisms of neutrophils and the tumor-suppressive mechanisms of CXCR2 inhibition challenging." (PMID 38898176, 2024). "Tumour size in PDAC correlates with the level of CXCR2 expression." (PMID 38384463, 2024). "Furthermore, VEGFA, KDR, CXCR1 and CXCR2 were significantly upregulated in tumour samples compared with paired normal samples, except for VEGFB, whose expression was not statistically significant." (PMID 38426619, 2024). "Yet, the mechanisms by which neutrophils promote tumor progression in humans, as well as how CXCR2 inhibition could potentially serve as a cancer therapy, remain elusive." (PMID 38898176, 2024). "The recruitment of CAR-T cells at the tumor site was significantly enhanced with the aid of ectopic CXCR2, and CXCR2 CAR-T cells also demonstrated superior effectiveness in treating PDAC compared to control counterparts, with an increased proportion of effective memory T cells." (PMID 38430267, 2024). "Many agents targeting IL-8 and IL-8 receptors, and many combined strategies are under clinical investigation: monoclonal antibodies, neutralizing antibodies, direct antagonists, antibodies anti-CXCR1 and -CXCR2, in different tumor types, with the aim of increasing the anti-tumoral efficacy." (PMID 38443899, 2024).
tumor (continued). "Engineering CAR T-cells to coexpress chemokine receptors, such as CXCR1 or CXCR2 for IL-8-secreting ovarian or pancreatic tumors, may be an additional strategy to direct cells to the tumor and mitigate on-target/off-tumor toxicity in other tissues." (PMID 39674824, 2024). "Previous studies have reported that the CXCL1/CXCR2 axis is involved in tumor immune evasion." (PMID 38510750, 2024). "Moreover, CXCL5 and IL-1β secreted by tumor cells correlated significantly to PMN-MDSCs accumulation, and antagonism against IL-1β or CXCR2 retarded tumor growth." (PMID 38649887, 2024). "CXCR2+ MDSCs promote tumour expansion, metastasis, EMT and T-cell depletion in breast cancer." (PMID 38475858, 2024). "Additionally, CXCL1 and CXCL2 have been shown to promote the resistance of HCC cells to sorafenib, whereas C-X-C motif chemokine receptor 2 inhibition induces reprogramming of the tumor immune environment that promotes immune checkpoint inhibition in MASH-HCC." (PMID 39621069, 2024). "IL-8, a key pro-inflammatory chemokine, signals through two G protein-coupled receptors (GPCRs), CXCR1 and CXCR2, and has been shown to be upregulated in PCa and other cancers, including breast, lung, and pancreatic, promoting tumour cell proliferation and migration." (PMID 39199570, 2024). "The overexpression of CXCR2 in LNCaP cells was previously shown to increase tumor growth." (PMID 39766038, 2024). "Indeed, tumor-infiltrating CXCR2+ neutrophils play a significant role in shielding tumor cells from CD8+ T and NK cell-mediated cytotoxicity." (PMID 39114657, 2024). "Furthermore, RCT001, an optimized CXCR2 inhibitor, enhances the efficacy of anti-CTLA4 + anti-PD1 therapies by inhibiting tumor-associated M2 macrophages and tumor-associated neutrophils." (PMID 39014460, 2024). "Moreover, another study has suggested that the overexpression of CXCL1 and CXCR2 has a positive effect on tumor growth by recruiting Tregs." (PMID 38515216, 2024). "Interestingly, treatment with AZD-5069, a CXCR2 inhibitor, attenuates invasion and proliferation of tumor spheroids by blocking direct contact with neutrophils." (PMID 38898176, 2024). "We could also engineer a more biomimetic system by building an endothelial lumen around the central channel to assess the effect of CXCR2 inhibition on neutrophil extravasation into the tumor tissue." (PMID 38898176, 2024). "T-cell proliferation assays in the tumor-bearing setting demonstrated that loss of neutrophil-specific Cxcr2 does not attenuate the immunosuppressive function of neutrophils in the metastatic niche." (PMID 38358352, 2024). "Although CCR1 and CXCR2 on myeloid cells could be involved in tumor progression, it remains elusive what effect would be observed if both of those are blocked." (PMID 38750114, 2024). "CXCR2-driven NE cells are critical for the tumor microenvironment by providing a survival niche for AR+ luminal cells; consequently, combination of CXCR2 inhibition and AR targeting effectively inhibited lineage plasticity and NE transition in mouse xenograft models." (PMID 39363904, 2024). "Recent studies have discovered that stem cell markers, such as doublecortin-like kinase (DCLK1) and RNA modification by methyltransferase-like 3 (METTL3), play a role in recruitment of CXCR2+ MDSCs to modulate tumor immunity through the CXCL1-CXCR2 axis in CRC mouse models." (PMID 38750114, 2024). "Firstly, we found that CXCR2 showed great importance in senescence and tumor." (PMID 38184636, 2024). "Recent studies have discovered that stem cell markers such as doublecortin-like kinase (DCLK1) and RNA modification by methyltransferase-like 3 (METTL3) also play a role in the recruitment of CXCR2+ TANs to modulate tumor immunity through the CXCL1−CXCR2 axis in CRC mouse models." (PMID 39795864, 2024). "Indeed, the CXCR2 inhibitor called SB225002 led to reduced tumor growth as well as incomplete vascular mimicry structures in animal models." (PMID 36980182, 2023).
tumor (continued). "Additionally, we examined CXCR2 expression on myeloid cells in the TME and found that tumor-infiltrating neutrophils also highly expressed CXCR2 compared to other cell populations." (PMID 38067390, 2023). "Administration of IL-8 antibodies via SX-682 (a small molecule inhibitor targeting CXCR1 and CXCR2) reduces the number of immunosuppressive myeloid-derived suppressor cells (MDSCs) within the tumor microenvironment and enhances the efficacy of adoptive cell therapy with NK cells." (PMID 37143649, 2023). "Our results indicated that the combination of Plasmodium infection and Gem treatment significantly suppressed tumor metastasis and EMT, and these suppressions were potentially associated with the blockade of CXCR2/TGF-β-mediated PI3K/Akt/GSK-3β/Snail signaling pathway." (PMID 37916167, 2023). "Moreover, it has been demonstrated in multiple preclinical studies that combination treatments of a CXCR2 antagonist with an immune checkpoint inhibitor inhibited tumor growth, resulting in improved survival." (PMID 36903345, 2023). "Thus, researchers have generated a CAR-T cell strategy capable of expressing IL-8 receptors (CXCR1 or CXCR2) thereby enhancing their capacity of infiltrating solid tumors, consequently exerting an anti-tumor effect." (PMID 36717905, 2023). "In this study, we used two different types of syngeneic mouse tumor models (prostate and colorectal) to examine if pharmacological blockade of CXCR2 could reduce RT-induced neutrophil recruitment into the tumor." (PMID 38067390, 2023). "While much more MPO+ CXCR2+ neutrophils are found in LN(+) tumor tissue than in LN(‐) tumor tissue." (PMID 36670069, 2023). "Furthermore, the delivery of a CXCR2 inhibitor by TAS2R9-targeted liposomes significantly reduced cancer cell proliferation and constrained tumor growth through the inhibition of the CXCL-CXCR2 axis." (PMID 36986488, 2023). "Another myeloid cell-based approach involves inhibiting certain cytokines, chemokines, or their receptors, including CXCR2 (C-X-C motif chemokine receptor 2) and targeting checkpoints, thereby increasing T-cell filtration into the tumor and effectively killing tumor cells as a result." (PMID 37373398, 2023). "Importantly, the knockdown of CXCR2, a key chemotactic receptor for neutrophils, to inhibit immune infiltration of neutrophils can lead to a T cell-dependent suppression of tumor growth." (PMID 37868992, 2023). "One of these involves tumour secretion of chemokines, including CXCR2." (PMID 36902776, 2023). "Collagen I depletion in tumor tissue results in enhanced oncogenesis and increased expression of Cxcl5, which causes recruitment of myeloid-derived suppressor cells and suppression of CD8 + T cells in a CXCR2/CCR2-dependent manner." (PMID 36906534, 2023). "While we do not expect all melanocytic cells in the Braf/Pten/Cxcr2WT tumors to be CXCR2 positive due to variation caused by cell cycle and differentiation status, we should not see any CXCR2 positivity in the Braf/Pten/Cxcr2−/− tumor cells." (PMID 37270599, 2023). "We then examined CXCR2 expression on neutrophils and other immune cells in the tumor-bearing mice." (PMID 38067390, 2023). "In addition, the glutamate-leucine-arginine positive (ELR+) CXC chemokines, which all interact with CXCR2, directly function as growth factors for tumor cells and stimulate metastases." (PMID 36903345, 2023). "More MPO+ CXCR2+ neutrophils were identified in tumor tissue than in normal adjacent tissue." (PMID 36670069, 2023). "Notably, the combination of AB680, anti‐PD‐1 antibody, and CXCR2 inhibitor showed superior synergistic tumor suppression in vivo, providing an efficient and promising therapeutic strategy for PDAC." (PMID 37867243, 2023).
tumor (continued). "We demonstrated that the CXCLs/CXCR2 axis likely translates the RT-induced DNA-sensing pathway signals leading to the observed RT-induced neutrophilic infiltration into the tumor, which is an early innate inflammatory immune response of RT that leads to further downstream immune-modulatory effects." (PMID 38067390, 2023). "However, neutrophils in the gem group expressed high levels of CXCR2, LRG1, and LCN2 genes, which are associated with tumor progression and metastasis." (PMID 37324492, 2023). "Furthermore, both myeloid cells and their CXCR2 expression increased in the periphery of tumor-bearing mice compared with the control mice." (PMID 38067390, 2023). "Therefore, emerging research suggests that combination therapies of monoclonal anti-CXCL8 antibodies or CXCR1/CXCR2 antagonists with standard anti-tumor (immuno)therapy can tackle the tumor immune escape and provide further benefit in anti-tumor treatment." (PMID 36725964, 2023). "IL-8 secreted by tumor cells induces lytic NETosis via the CXCR2-mediated pathway." (PMID 36050539, 2023). "Therefore, ACKR1 has the potential to be a therapeutic target for treating various cancers, particularly if both ACKR1 and CXCR2 are expressed in tumor cells." (PMID 37108425, 2023). "Considering that radiotherapy is widely used in tumor treatment, whether reducing MDSCs migration by inhibiting CXCR2 and CCR2 signaling can promote the therapeutic effect of radiotherapy will be the focus of our subsequent study." (PMID 37268941, 2023). "CXCR2 recruits myeloid derived suppressor cells (MDSCs) to the tumor microenvironment." (PMID 36903345, 2023). "Furthermore, CXCR2 and CXCLs have been shown to be involved in the recruitment of neutrophils into the tumor." (PMID 38067390, 2023). "Additionally, CXCL8 can be involved in the proliferation, self-renewal, and recruitment of CXCR1/CXCR2-expressing cancer stem cells, which are known to promote tumorigenesis, tumor maintenance, metastasis, and drug resistance in many different cancers." (PMID 36725964, 2023). "The change of cytokine secretion profile may be one of the mechanisms that CXCR2 knockdown led to decreased tumor killing activity." (PMID 37403022, 2023). "CXCR2 blockade significantly reduced the tumor growth delay induced by radiation." (PMID 38067390, 2023). "Interestingly, tumor-bearing increased CXCR2+ cell percentages in most types of immune cells examined." (PMID 38067390, 2023). "Furthermore, C-X-C motif chemokine receptor 2 (CXCR2) antagonist SB225002 enhanced the docetaxel (DTX) effects on tumor growth by decreasing BCSCs in CCL20high-expressing tumors." (PMID 36859354, 2023). "Consistent with the tumor growth results, CXCR2 blockade also shortened RT-induced survival." (PMID 38067390, 2023). "We also sought to investigate if lymphoid cells express CXCR2 in tumor-bearing mice." (PMID 38067390, 2023). "Thus, we used flow cytometry to examine the CXCR2 expression on both myeloid and lymphoid populations in the spleens from control and RM-9 tumor-bearing mice." (PMID 38067390, 2023). "Furthermore, these CXCR2−/− OT mice displayed a significant reduction in tumor burden at all time points and a significant extension in overall survival compared to CXCR2+/+ WT OT controls." (PMID 36614196, 2023). "The expression of CXCR2 on M-MDSCs may change with different spatial locations, such as tumor in situ and lung metastasis." (PMID 37268941, 2023). "Overall, SX-682 produced inhibition of tumor volume comparable to that of CXCR2 loss in melanocytes but did not impact tumor formation as significantly." (PMID 37270599, 2023). "We showed that tumor-infiltrating neutrophils express a lower level of CXCR2 than peripheral neutrophils, which could be a result of partial CXCR2 internalization after CXCLs/CXCR2 binding." (PMID 38067390, 2023).